STK11 (serine/threonine kinase 11)
Diseases named in the same sentence as STK11 in open-access papers (continued):
Sharing a sentence is not in itself a finding about the gene and the disease.
ischemia (4 papers, 2017 to 2025). A hypoperfusion of the BLOOD through an organ or tissue caused by a PATHOLOGIC CONSTRICTION or obstruction of its BLOOD VESSELS, or an absence of BLOOD CIRCULATION. "It was demonstrated that STK11 is critical in maintaining normal cardiac function under aerobic condition or during recovery after ischemia." (PMID 28349069, 2017).
leukemia (4 papers, 2012 to 2022). A malignant (clonal) hematologic disorder, involving hematopoietic stem cells and characterized by the presence of primitive or atypical myeloid or lymphoid cells in the bone marrow and the blood. "However, to the best of our knowledge, no leukemia cases have so far been reported in this condition and somatic STK11 P280S mutations were previously reported in only two children with ALL: one child with B-ALL and one with Philadelphia chromosome–like acute lymphoblastic leukemia (Ph-like ALL)." (PMID 36824296, 2022).
Pancytopenia (4 papers, 2017 to 2020). An abnormal reduction in numbers of all blood cell types (red blood cells, white blood cells, and platelets). "Hematopoietic-specific Stk11-deficient mice died from pancytopenia." (PMID 33236987, 2020). "Hematopoietic stem cell-specific deletion of Stk11 led to limited mouse survival for up to 28 days due to pancytopenia." (PMID 33236987, 2020).
squamous non-small-cell lung cancer (4 papers, 2017 to 2022). "STK11 exon 1–2 mutations such as potential oncogenic activity in non-squamous non-small-cell lung cancer." (PMID 36499466, 2022).
thyroid cancer (4 papers, 2019 to 2025). "Of note, EIF1AX mutations were found almost exclusively in HRAS-, KRAS-, and NRAS-mutant thyroid cancers (p<0.05), whereas STK11 mutations were found in greater proportion of HRAS-mutant NSCLC compared to the other HRAS-mutant cancer types." (PMID 37503077, 2023). "Germline STK11 mutations cause Peutz–Jeghers syndrome (PJS) and confer increased thyroid cancer risk." (PMID 40600748, 2025).
Alzheimer disease (3 papers, 2021 to 2024). A progressive, neurodegenerative disease characterized by loss of function and death of nerve cells in several areas of the brain leading to loss of cognitive function such as memory and language. "The variant is an intragenic SNP in the STK11 gene and associated with the presence versus absence of psychosis in Alzheimer disease (AD) cases." (PMID 38412862, 2024).
coronary artery disease (3 papers, 2017 to 2023). "However, despite the potential importance of STK11 activity in terms of regulating cardiovascular systems, very few studies had been conducted on STK11 gene and genetic variants in heart diseases, especially in coronary artery disease." (PMID 28349069, 2017).
diffuse large B-cell lymphoma (3 papers, 2012 to 2025). "In general, at least one of the genes that encode immune stimulators exhibited a positive correlation with PEBP1/STK11 expression across all cancer types, with the exception of CHOL, ESCA, UCS, and diffuse large B-cell lymphoma (DLBC)." (PMID 40806276, 2025).
gastric adenocarcinoma (3 papers, 2017 to 2025). "We find that the peptide hormone gastrin induces autophagy in two gastric adenocarcinoma cell lines via the STK11-PRKAA2-ULK1 pathway." (PMID 28109268, 2017). "In this study, we find that gastrin treatment induces autophagy in the gastric adenocarcinoma cell lines AGS-Gr and MNK45, concomitant with the activation of the STK11-PRKAA2-ULK1 signaling cascade." (PMID 28109268, 2017). "Natural killer (NK) cells, both in their resting and activated states, displayed a positive correlation with the co-expression of PEBP1/STK11 across a broad spectrum of cancers, predominantly within the gastrointestinal tract (excluding CHOL and gastric adenocarcinoma (STAD))." (PMID 40806276, 2025).
gastric polyps (3 papers, 2011 to 2025). "This analysis did not reveal a statistically significant association between the gastric polyp phenotype and the location of STK11 mutations." (PMID 35224145, 2022).
gynecological cancers (3 papers, 2012 to 2025). "However, nine (9/35, 25.71%) PJS unrelated families with point variants (n = 5) or large deletions (n = 4) in the STK11 exon one developed cancers in probands and/or the affected relatives were associated with the digestive system, as well as with lung, breast, and gynecological cancers." (PMID 36033506, 2022).
lipid metabolism disorder (3 papers, 2023 to 2025). "This study provides convincing evidence that JHP may partially ameliorate early NONFH by restoring the balance of lipid metabolism disorder and reversing pathological events during early NONFH progression by regulating the NAMPT/STK11/HMGCR/ACAT1 axis." (PMID 40988117, 2025).
mucinous carcinomas (3 papers, 2022 to 2025). "- STK11 (LKB1) (tumor suppressor): mutated in 33–55% of GAS (including minimally differentiated mucinous carcinomas, MDA)." (PMID 40732715, 2025).
neurofibromatosis type 1 (3 papers, 2021 to 2022). A clinically heterogeneous, neurocutaneous genetic disorder characterized by cafe-au-lait spots, iris Lisch nodules, axillary and inguinal freckling, and multiple neurofibromas. "Only 10% of PDACs are linked to genetic mutations such as BRCA2, STK11/LKB1, CFTR, and PRSS1 or to familial syndromes such as Von Hippen-Lindau disease (VHL), multiple endocrine neoplasia syndrome type 1 (MEN-1), and neurofibromatosis type 1 (NF-1)." (PMID 36611999, 2022).
pneumonia (3 papers, 2022 to 2025). An acute, acute and chronic, or chronic inflammation focally or diffusely affecting the lung parenchyma, caused by an infection in one or both of the lungs (by bacteria, viruses, fungi, or mycoplasma.). "During pneumonia induced by either encapsulated or non-encapsulated Spneu, Stk11-ΔM and control mice had comparable bacterial loads and inflammatory responses in the lung, with the exception of lower TNFα levels in Stk11-ΔM mice after infection with the non-encapsulated strain." (PMID 36096803, 2022).
prostatic intraepithelial neoplasia (3 papers, 2016 to 2025). "Notably, conditional STK11/LKB1 knockout mice have been shown to develop atypical hyperplasia and prostatic intraepithelial neoplasia." (PMID 40171220, 2025). "In addition, expression of human serine/threonine kinase 11 (also known as liver kinase B1, LKB1), which directly activates AMPK, was markedly diminished in high-grade prostatic intraepithelial neoplasia lesions and entirely abolished in adenocarcinomas." (PMID 36769263, 2023).
small cell lung carcinoma (3 papers, 2016 to 2025). Small cell lung cancer (SCLC) is a highly aggressive malignant neoplasm, accounting for 10-15% of lung cancer cases, characterized byrapid growth, and early metastasis. "Non–small cell lung cancer cell lines with KRAS/STK11 comutations were more sensitive to a CHK1/2 inhibitor than cell lines without STK11 comutations." (PMID 36381660, 2022).
chronic pancreatitis (2 papers, 2022 to 2026). A chronic inflammatory process causing damage and fibrosis of the pancreatic parenchyma. "Mice with postnatal duct-specific deletion of HNF6 or LKB1 (also known as serine/threonine kinase 11 (STK11)) exhibit pancreatic duct dilation, which is associated with chronic pancreatitis, including ADM, acinar proliferation and apoptosis, inflammatory infiltration, fibrosis and lipomatosis." (PMID 35327494, 2022).
ciliopathies (2 papers, 2019 to 2023). "STK11, a serine/threonine kinase, has been reported to be downregulated in human diseases associated with ciliopathies and functions as a tumor suppressor." (PMID 31636950, 2019). "Given the clear evidence that decreased expression of STK11 in human diseases is associated with ciliopathies, we conclude that STK11 is a physiological regulator to enforce ciliated cell fate commitment and multiciliogenesis, ensuring the normal program of ciliated cell differentiation." (PMID 31636950, 2019).
Inherited cancer syndromes (2 papers, 2003 to 2023). "In contrast to a number of other inherited cancer syndromes, cancer risks associated with germline LKB1/STK11 mutations cancer risks are not so site specific." (PMID 12865922, 2003).
Intussusception (2 papers, 2021 to 2023). An abnormality of the intestine in which part of the intestine invaginates (telescopes) into another part of the intestine. "While previous studies showed the median age of diagnosis and first gastrointestinal symptom onset in patients with null STK11 mutations to be 17 and 10 years, respectively, the median diagnostic age of our patients was 18 years, with intussusception as the most frequent first symptom." (PMID 36874343, 2023).
meningioma (2 papers, 2024). A generally slow growing tumor attached to the dura mater. "Variants typical for angiomatous (brain) meningioma are PIK3CA, KIT, PTPN11, CDH1, SMAD4, and SMARCB1; the variants typical for psammomatous meningioma are APC, FGFR2, HNF1A, STK11, and JAK3." (PMID 38476782, 2024).
metastatic melanoma (2 papers, 2024 to 2025). A melanoma that has spread from its primary site to another anatomic site. "Mutations or phenotypic defects in STK11 have been significantly associated with immunotherapy resistance in patients with metastatic melanoma." (PMID 39530091, 2024). "Bemcentinib in the context of first line metastatic melanoma treatment (NCT02872259) did not increase patient response or survival, and a first line combination treatment trial in STK11-mutant NSCLC was recently discontinued (NCT05469178, 58)." (PMID 40539073, 2025).
neuroendocrine carcinoma (2 papers, 2020 to 2021). A malignant neuroendocrine neoplasm composed of cells containing secretory granules that stain positive for NSE and chromogranin.
ovarian serous carcinoma (2 papers, 2015 to 2022). "A recent report of a conditional mouse model for serous ovarian carcinoma determined that loss of Stk11 in the context of Pten loss within the OSE leads to the development of high-grade papillary serous ovarian carcinomas." (PMID 26068970, 2015). "STK11 loss has already been shown in ovarian serous carcinoma and may favor mTOR activation." (PMID 35965534, 2022).
serous cystadenoma (2 papers, 2020 to 2021). A serous neoplasm in which the cysts and papillae are lined by a single layer of cells without atypia, architectural complexity or invasion. "Deletion of STK11/LKB1 in the pancreas also resulted in the development of serous cystadenomas." (PMID 32423157, 2020).
tauopathy (2 papers, 2020 to 2021). Neurodegenerative disorders involving deposition of abnormal tau protein isoforms (tau proteins) in neurons and glial cells in the brain. "Additionally, dysregulation of STK11 has been shown to contribute to Aβ accumulation and tauopathy AD-associated." (PMID 32518535, 2020). "Problem 2 asked participants to predict compounds that bind the Tauopathy pro-targets AURKA, PAK1, FGFR1, and STK11 and avoid the Tauopathy anti-targets PAK3, MAP3K7, and PIK3CA." (PMID 34520464, 2021). "Problem 2 asked participants to predict compounds that bound the Tauopathy pro-targets, AURKA, PAK1, FGFR1, and STK11 and did not bind PAK3, MAP3K7, and PIK3CA." (PMID 34520464, 2021).
thymoma (2 papers, 2017 to 2022). A neoplasm arising from the epithelial cells of the thymus. "Only two B3 thymomas had a mutation in noncoding regions of the SMARCB1 and STK11 gene respectively." (PMID 27844328, 2017). "Two (10%) B3 thymomas had a mutation in non-coding regions of SMARCB1 and STK11." (PMID 35884448, 2022).
(CMMRD) syndrome (1 paper, 2022).
anaplastic thyroid carcinoma (1 paper, 2016). "Mutations in STK11 were also reported in other types of cancer including poorly differentiated and anaplastic thyroid carcinoma." (PMID 27494611, 2016).
deficient (1 paper, 2022). "We also suggest that the Stk11-Ptbp1-Scf axis may be a potential new therapeutic avenues for DC deficient syndrome for which there are no treatment options right now." (PMID 35115536, 2022).
emphysema (1 paper, 2021). "The cytosolic transport (RNF126, PLEKHJ1, VPS51, and AP1G1), target of rapamycin (mTOR) signaling (PIK3CA, STK11, RPS6KB2, and PRR5), regulation of translation, metabolic regulation, and apoptosis are involved in the percent emphysema-associated network." (PMID 34777474, 2021).
endocrine cancers (1 paper, 2025). "Further analysis of additional ECM molecules, including VTN, EMC1, THBS3, and CLEC3B revealed a positive correlation trend with PEBP1/STK11 co-expression in endocrine cancers, while correlations in other cancer types varied, suggesting a context-dependent relationship." (PMID 40806276, 2025). "Similarly, collagens and other ECM structural components displayed largely negative correlations with PEBP1/STK11 co-expression, with the most frequent exceptions found in endocrine cancers, particularly in THYM." (PMID 40806276, 2025).
endometrioid ovarian carcinoma (1 paper, 2025). "Additionally, we identified deletions in genes TSC2 and STK11 that have not been previously reported in endometrioid ovarian carcinoma." (PMID 40981433, 2025).
esophageal adenocarcinoma (1 paper, 2021). A malignant tumor with glandular differentiation arising predominantly from Barrett mucosa in the lower third of the esophagus.
germ cell tumor (1 paper, 2025). A benign or malignant, gonadal or extragonadal neoplasm that originates from germ cells. "KRAS mutations are present in germ cell tumors (12%) while STK11 are rare, found in less than 1% of mutations identified based on TCGA analysis." (PMID 40723253, 2025).
gestational diabetes (1 paper, 2017). Carbohydrate intolerance first diagnosed during pregnancy. "AMPK and STK11 are related to the susceptibility of T2DM, gestational diabetes, muscle disease, and cancer." (PMID 28775741, 2017).
gout (1 paper, 2021). A condition characterized by painful swelling of the joints, which is caused by deposition of urate crystals. "Decreases in PRKCZ and STK11 methylation were also associated with higher numbers of first-degree relatives who also had gout." (PMID 33493135, 2021). "The results indicated that hypomethylation in PRKCZ and STK11 was associated with familial clustering of gout." (PMID 33493135, 2021). "Finally, decreased PRKCZ and STK11 methylation were associated with familial clustering of gout." (PMID 33493135, 2021). "Moreover, PRKCZ and STK11 methylation was also associated with familial clustering of gout." (PMID 33493135, 2021). "Interesting, methylation levels of PRKCZ and STK11 were lower for individuals with more extensive family histories of gout in first-degree relatives." (PMID 33493135, 2021). "The final nine surviving monocyte-specific differentially methylated CpG sites were mapped to eight genes (PRKCZ, CIDEC, VDAC1, CPT1A, BIRC2, BRCA1, STK11, and NLRP12) that have not previously been studied in the field of gout genetics." (PMID 33493135, 2021).
hereditary colorectal cancer (1 paper, 2021).
human papilloma virus infection (1 paper, 2015). An infectious process caused by a human papillomavirus.
hypercoagulability (1 paper, 2025). "In conclusion, JHP ameliorates early NONFH by regulating lipid metabolism, improving hypercoagulability, and restoring bone homeostasis through the NMNAT1/NMNAT3/NAMPT/STK11/HMGCR/ACAT1 axis." (PMID 40988117, 2025).
influenza infection (1 paper, 2020). "Transcription factor XBP1 and serine threonine kinase STK11, which are also dependent on ANXA1 for expression after influenza infection, have both been shown to be important in the regulation of autophagy." (PMID 32512864, 2020).
kidney stone (1 paper, 2025). "Among these, the expression of SUV39H1 and LCN2 was higher in the kidney stone model than in normal samples (p < 0.001), but the expression of FZD7 and STK11 was lower in the kidney stone model (p < 0.001)." (PMID 40171220, 2025). "Consistent with in vitro results, the expression of SUV39H1 and LCN2 was higher and the expression of FZD7 and STK11 was lower in the kidney stone model than in normal samples (p < 0.001)." (PMID 40171220, 2025).
Langerhans cell histiocytosis (1 paper, 2021). Langerhans cell histiocytosis (LCH) is a systemic disease associated with the proliferation and accumulation (usually in granulomas) of Langerhans cells in various tissues. "Similarly, in a chronic lymphocytic leukemia (CLL) patient, treatment with PI3Kδ inhibitor led to a switch from lymphocytic leukemia to Langerhans cell histiocytosis (LCH) with acquired BRAF V600E and STK11 mutations, and loss of expression of B-cell lineage markers such as PAX-5." (PMID 34298815, 2021).
Lewis lung carcinoma (1 paper, 2025).
Lung neuroendocrine tumours (1 paper, 2022).
lung tumors (1 paper, 2022). "Then, it was demonstrated that several lung tumors display deletions of chromosome 19, where the LKB1/STK11 gene is located." (PMID 35890085, 2022).
malignant mesothelioma (1 paper, 2024). A malignant neoplasm of the pleura or peritoneum, arising from mesothelial cells. "This is further supported by the expression of WT1, calretinin and D2–40, and rarely malignant mesotheliomas may harbour STK11 alterations." (PMID 38376618, 2024).
mesothelioma (1 paper, 2024). A usually malignant and aggressive neoplasm of the mesothelium which is often associated with exposure to asbestos. "Also, hormone receptors commonly expressed by STK11 adnexal tumours are uncommonly expressed in mesotheliomas." (PMID 38376618, 2024).
myeloproliferative neoplasm (1 paper, 2023). A clonal hematopoietic stem cell disorder, characterized by proliferation in the bone marrow of one or more of the myeloid (i.e., granulocytic, erythroid, megakaryocytic, and mast cell) lineages. "LKB1, also known as serine-threonine kinase 11 (STK11), has been identified as a tumor suppressor in various cancers, including gastrointestinal, non-small cell lung, pancreatic, cervical, and myeloproliferative neoplasms." (PMID 37607939, 2023).